XAB2 (XPA binding protein 2)
Description:
Involved in pre-mRNA splicing as component of the spliceosome. Involved in transcription-coupled repair (TCR), transcription and pre-mRNA splicing.
Synonyms: HCNP; SYF1; HCRN; NTC90
Tractability: Small molecule: a structure with a bound ligand is known. PROTAC: ubiquitination databases record sites on it; its protein half-life has been measured.
Gene: Protein-coding gene on chromosome 19 (7,619,523 to 7,629,565, reverse strand). Ensembl gene ENSG00000076924.
Subcellular location: Nucleus
Subcellular location (Human Protein Atlas): Nucleoplasm; Vesicles
Pathways (Reactome):
DNA Repair: Dual incision in TC-NER; Formation of TC-NER Pre-Incision Complex; Gap-filling DNA repair synthesis and ligation in TC-NER; Transcription-Coupled Nucleotide Excision Repair (TC-NER)
Disease: Dengue Virus-Host Interactions
Metabolism of RNA: mRNA Splicing - Major Pathway
Gene Ontology:
Molecular function: protein binding
Biological process: DNA-templated transcription; mRNA splicing, via spliceosome; transcription-coupled nucleotide-excision repair; generation of catalytic spliceosome for first transesterification step; cerebral cortex development; RNA processing
Cellular component: catalytic step 2 spliceosome; membrane; nucleoplasm; nucleus; post-mRNA release spliceosomal complex; post-spliceosomal complex; spliceosomal complex; U2-type catalytic step 1 spliceosome; U2-type catalytic step 2 spliceosome; Prp19 complex
Genetic constraint (gnomAD): Loss-of-function variants: 57 observed, 113.16 expected, observed/expected ratio (o/e) 0.5, 90% interval 0.41 to 0.63. The upper end of that interval is the gene's LOEUF score, 0.63, which puts it in group 2 of 6, group 1 being the genes least tolerant of losing a copy. Missense variants: 1,037 observed, 1,239.7 expected, observed/expected ratio (o/e) 0.84, 90% interval 0.79 to 0.88. Synonymous variants: 497 observed, 500.6 expected, observed/expected ratio (o/e) 0.99, 90% interval 0.92 to 1.07.
Homologues: Orthologues: chimpanzee XAB2 (100% identical), macaque XAB2 (99% identical), rat Xab2 (99% identical), dog XAB2 (99% identical), mouse Xab2 (99% identical), guinea pig XAB2 (98% identical), pig XAB2 (97% identical), rabbit XAB2 (86% identical), zebrafish xab2 (78% identical), tropical clawed frog xab2 (72% identical), Drosophila melanogaster fand (61% identical), Caenorhabditis elegans syf-1 (49% identical). Paralogues in human: CRNKL1 (20% identical), PRPF6 (15% identical).
Diseases named in the same sentence as XAB2 in open-access papers:
XAB2 is named in the same sentence as 29 diseases in open-access papers, as found by Europe PMC text mining. Sharing a sentence is not in itself a finding about the gene and the disease. The quoted sentences say what the papers report.
colorectal cancer (3 papers, 2015 to 2025). A primary or metastatic malignant neoplasm that affects the colon or rectum. "In another study, researchers analyzed the impact of several polymorphisms in DNA repair genes on the prognosis of colorectal cancer patients and didn’t find the association of XAB2 rs794078 G > A variant with the cancer prognosis." (PMID 26228655, 2015). "Notably, siRNA-mediated knockdown of XAB2 and PLK1 caused a virtually complete loss of proliferation, extending the known essential functions of these genes also to DLD1 colorectal cancer cells." (PMID 26755646, 2016).
gastric cancer (3 papers, 2021 to 2024). A primary or metastatic malignant neoplasm involving the stomach. "For XAB2 rs794078 G > A polymorphism, we found that AA genotype carriers had a significantly decreased risk for developing gastric cancer (OR = 0.33; 95% CI = 0.12–0.91) in comparison to those with GG genotype." (PMID 33557438, 2021). "To date, there are few studies to demonstrate the association of XAB2 polymorphism with the gastric cancer susceptibility." (PMID 33557438, 2021). "Our results showed that XAB2 rs794078AA genotype was associated with a significantly lower risk of gastric cancer compared with GG genotype with OR (95% CI) of 0.33 (0.12–0.91)." (PMID 33557438, 2021). "Several previous studies from our laboratory also provided the evidence that the effect of genetic variants in TNFSF15 and XAB2 on the susceptibility to gastric cancer could be modified by age." (PMID 35111412, 2022). "In conclusion, our results demonstrated that XAB2 rs794078 was associated with the risk of gastric cancer, which indicated that natural occurring genetic variation in key genes of NER may underlie the susceptibility to cancer." (PMID 33557438, 2021). "In order to investigate the role of XAB2 genetic variations in the development of gastric cancer, tagSNPs of XAB2 were selected and surveyed in this hospital-based case–control study." (PMID 33557438, 2021). "Our finding provided the first evidence that XAB2 rs794078AA genotype acted as a protective factor of gastric cancer." (PMID 33557438, 2021). "Our data showed that the smokers with XAB2 rs794078 AA genotype had a significantly decreased risk of gastric cancer compared with nonsmokers with GG genotype (OR = 0.11, 95% CI = 0.11–0.91, p = 0.040), suggesting rs794078 AA genotype was a protective factor for gastric cancer in smokers." (PMID 33557438, 2021).
lung carcinoma (3 papers, 2015 to 2024). "In this lung cancer case-control study, we didn’t find any association of XAB2 rs4134860 T > C polymorphism with the risk of NSCLC." (PMID 26228655, 2015). "Due to the important role of XAB2 in the TC-NER, we proposed that the genetic variants in XAB2 genes might contribute to the risk of lung cancer." (PMID 26228655, 2015). "Fortunately, we obtained four hub genes (MAPK3, MOV10, XAB2, and POLR2A), which potentially interact with BCAR1 and play carcinogenetic roles in lung cancer." (PMID 33001583, 2020).
Hyperglycemia (2 papers, 2021 to 2024). An increased concentration of glucose in the blood. "XPA binding protein 2 (XAB2) exerts as a regulator in hyperglycemia with chronic insulin." (PMID 34084770, 2021). "It was reported that XAB2 may exert as a regulator in hyperglycemia with chronic insulin." (PMID 39777224, 2024).
lung adenocarcinoma (2 papers, 2020 to 2021). A carcinoma that arises from the lung and is characterized by the presence of malignant glandular epithelial cells. "MOV10, encoding Mov10 RISC complex RNA helicase, was reported to be highly expressed with POLR2A, MAPK3, and XAB2 in 95% of 54 lung adenocarcinoma (LUAD) cases with poor prognosis." (PMID 34616428, 2021). "The K‐M plotter database indicated that high expression of POLR2A, MAPK3, MOV10, and XAB2 predicted poor prognosis in lung adenocarcinoma." (PMID 33001583, 2020). "High expression of POLR2A, MAPK3, MOV10, and XAB2 predicted poor prognosis in lung adenocarcinoma, as verified by the K‐M plotter database." (PMID 33001583, 2020).
non-small cell lung carcinoma (2 papers, 2015 to 2018). A group of at least three distinct histological types of lung cancer, including non-small cell squamous cell carcinoma, adenocarcinoma, and large cell carcinoma. "In this case-control study in a Chinese population, we found that two tag SNPs (rs794078 and rs4134816) in XAB2 were associated with significantly decreased risk of development non-small cell lung cancer." (PMID 26228655, 2015).
osteosarcoma (2 papers, 2017 to 2021). A usually aggressive malignant bone-forming mesenchymal neoplasm, predominantly affecting adolescents and young adults. "In a previous study investigating the role of XAB2 in HR in the U2OS human osteosarcoma cell line, siRNA-mediated depletion of XAB2 resulted in a decrease in CPT-induced chromatin-bound RPA, as assessed by flow cytometry analysis, which was interpreted as indicative of defective end resection." (PMID 34500463, 2021). "First, we examined whether PRPF8 and XAB2 form a complex in the human osteosarcoma U2OS cell line, by performing co-IP analysis." (PMID 29212152, 2017).
Ascites (1 paper, 2022). Accumulation of fluid in the peritoneal cavity (between the layers of the peritoneum that lines the abdomen). "The expression levels of HELQ (RR 5.7, 95% CI 1.7-19.2) and XAB2 (RR 3.2, 95% CI 0.9-10.8) in ascites tumor cells were positively correlated to the risk of platinum resistance." (PMID 35392433, 2022). "In summary, our findings demonstrated that immunocytochemistry for HELQ and XAB2 expressions in ascites tumor cells are applicable in prediction of the primary response to chemotherapy and prognosis." (PMID 35392433, 2022).
autoimmune disease (1 paper, 2015). A disorder resulting from loss of function or tissue destruction of an organ or multiple organs, arising from humoral or cellular immune responses of the individual to their own tissue constituents. "There were several studies to evaluate the role of XAB2 genetic variants in complex autoimmune disease." (PMID 26228655, 2015).
breast carcinoma (1 paper, 2024). "WES analysis of the patient’s breast cancer sample revealed three unique nonsynonymous SNVs in the APOB, TBC1D32, and XAB2 genes." (PMID 38243282, 2024).
colon adenocarcinoma (1 paper, 2025). "Based on the TCGA dataset, XAB2 was found to be highly expressed in various cancer types, including colon adenocarcinoma (COAD) and rectal adenocarcinoma (READ)." (PMID 40069750, 2025).
colon cancer (1 paper, 2020). "Based on our network, CLK2, INTS3, and XAB2 may function as oncoproteins because that the high expression of these SFs showed poor survival of colon cancer." (PMID 32962686, 2020).
colorectal adenocarcinoma (1 paper, 2025). The most common type of colorectal carcinoma. "The high expression of XAB2 was subsequently validated using data from unpaired and paired colorectal adenocarcinoma (COADREAD) cohorts in The Cancer Genome Atlas (TCGA)." (PMID 40069750, 2025).
diabetes (1 paper, 2021). "Four genes including GAB2, LMNB2, XAB2 and RBM39 are involved in the regulation of diabetes, fat and insulin signaling, according to text mining." (PMID 34084770, 2021).
DNA repair disorders (1 paper, 2021). "Thus, XAB2 functionally links the spliceosomal response to DNA damage with R-loop processing with important ramifications for transcription-coupled DNA repair disorders." (PMID 34039990, 2021).
melanoma (1 paper, 2022). A malignant, usually aggressive tumor composed of atypical, neoplastic melanocytes. "The result showed that SMARCA4, XAB2 and NUDT1 were potent markers for the overall survival (OS) and disease‐specific survival (DSS) and SMARCA4 was shown to correlate with XAB2 and NUDT1 expression in melanoma patients." (PMID 36317703, 2022).
ovarian carcinoma (1 paper, 2022). A malignant neoplasm originating from the surface ovarian epithelium. "Our study has confirmed that ovarian cancer patients with the high expression of HELQ or XAB2 had decreased PFS and OS, respectively." (PMID 35392433, 2022). "NER-related genes including HELQ and XAB2 expressions were determined via immunocytochemistry in ascites cell samples from 92 ovarian cancer patients prior to primary cytoreduction surgery." (PMID 35392433, 2022). "However, the mechanism of HELQ and XAB2 leading to platinum resistance in ovarian cancer needs further exploration." (PMID 35392433, 2022).
pancreatic cancer (1 paper, 2016). "Consistently, homozygous XAB2 and PLK1 knockout mice display an early embryonic lethal phenotype and knockdown of XAB2 was reported to induce widespread cell death in human bladder, cervix and pancreatic cancer." (PMID 26755646, 2016).
progeroid syndrome (1 paper, 2021). A group of rare genetic disorders which mimic physiological aging, making affected individuals appear to be older than they are. "The finding that XAB2 is released from RNA targets in progeroid Csbm/m developing livers makes it attractive to test whether DNA damage-driven changes in RNA processing are causal to the premature onset of age-related pathological symptoms seen in TC-NER progeroid syndromes and during natural aging." (PMID 34039990, 2021).
rhabdomyosarcoma (1 paper, 2018). A rare aggressive malignant mesenchymal neoplasm arising from skeletal muscle. "It was shown that XAB2 is associated with RARα and histone deacetylase 3 in cell nuclei, and overexpression of XAB2 inhibits ATRA-induced cell differentiation in a human rhabdomyosarcoma cell line." (PMID 29301374, 2018).
viral infection (1 paper, 2021). "Differentially expressed genes in the viral infection category (174 genes) indicated that keratinocytes had down-regulated genes involved in host gene transcription (DDX56, SMARCA2) and RNA transportation and processing (NUP98, RAE1, XAB2, RBM17, EXOSC10)." (PMID 34552595, 2021).
xeroderma pigmentosum (1 paper, 2015). Xeroderma pigmentosum (XP) is a rare genodermatosis characterized by extreme sensitivity to ultraviolet (UV)-induced changes in the skin and eyes, and multiple skin cancers. "In the present study, we analyzed the protein-protein interaction between human Dbr1 and the factors found in the IL complex, and found that xeroderma pigmentosum, complementeation group A (XPA)-binding protein 2 (Xab2) can interact with hDbr1 among them." (PMID 25671812, 2015).
cancer (13 papers, 2010 to 2025). A tumor composed of atypical neoplastic, often pleomorphic cells that invade other tissues. "This is the first study to investigate the association of XAB2 polymorphisms with the risk for developing cancer." (PMID 26228655, 2015). "Polymorphisms in the XAB2 gene may have an effect on the capability of DNA repair and further contribute to the risk of developing various cancers." (PMID 33557438, 2021). "Due to the important roles of XAB2 in NER, the functional genetic variants in XAB2 may lower DNA repair capability and further contribute to the occurrence of cancer." (PMID 33557438, 2021). "In addition, depletion of splice factors including SNRPD3, SF3B1, and XAB2 in cancer cells was found to cause defects in sister chromatid cohesion via aberrant splicing of soronin pre‐mRNA." (PMID 28296343, 2017). "But the most remarkable pro-cancer RAD52 phenotype is seen in cancer cells deficient in any of the following DNA repair proteins: BRCA1, BRCA2, PALB2, XAB2 or RAD51 paralogs: RAD51B, RAD51C, RAD51D, XRCC2 and XRCC3." (PMID 34887904, 2021). "Overexpression of RAD51 or RAD52 rescued the XAB2 defects and XAB2 loss was synthetically lethal with RAD52 inhibition, providing potential perspectives in cancer therapy." (PMID 34500463, 2021). "Given the role of XAB2 in DDR, it may be implicated in cancer development and resistance to DNA-damage-inducing chemotherapy medications." (PMID 40069750, 2025). "Therefore, it will be interesting to investigate whether XAB2 can serve as a new anti-mitotic target for cancer therapy." (PMID 27735937, 2016). "Other important candidates such as splicing factors PUF60 and XAB2 and TRAP1, a chaperone upregulated in various cancers and essential for maintaining mitochondrial homeostasis were downregulated in LSCs." (PMID 31448224, 2019). "We validated XAB2 as a novel TMZ sensitizer using clonogenic assays with NCH644 cells (GBM cancer stem-like cell line) and U87 cells (GBM adherent cell line) expressing a control, non-silencing shRNA (shCTRL) or two independent shRNAs targeting XAB2." (PMID 34500463, 2021). "Our data suggest that strategies targeting XAB2 and/or RAD52 may help improve the therapeutic outcome of cancer patients treated with seDSBs-inducing DNA damaging agents." (PMID 34500463, 2021). "Namely, we speculate that therapeutic targeting of splicing factors, including PRPF8 or XAB2, has the potential to disrupt BRCA1 function in cancer cells, which is known to correlate with improved therapeutic response to clastogens." (PMID 29212152, 2017). "More importantly, this quantitative approach identifies genes potentially involved in cancer that have not been previously identified, such as KLHL21, KIFC1, and XAB2." (PMID 20454660, 2010).
infection (2 papers, 2016 to 2025). The state of being infected such as from the introduction of a foreign agent such as serum, vaccine, antigenic substance or organism. "The possible functions of XAB2 during infection remain to be investigated, especially since siRNA silencing it induced a noticeable cytotoxic effect." (PMID 40193402, 2025). "Here we found three genes H2AFX, XAB2 and PAPD7 were up regulated by the infection." (PMID 27354008, 2016).
tumor (2 papers, 2022 to 2025). "In the training cohort of 60 patients, better survival was strongly associated with low expression of HELQ and XAB2 in ascites tumor cells." (PMID 35392433, 2022). "Consistently, XAB2 knockdown significantly inhibited tumor growth, while XAB2 overexpression significantly promoted tumor growth." (PMID 40069750, 2025). "To validate the reliability of HELQ and XAB2 results in ascites tumor cells, we also determined the expression of HELQ and XAB2 in paired primary tumor tissues." (PMID 35392433, 2022). "Then, we investigated the relative expression of HELQ and XAB2 in ascites tumor cells utilizing ROC curves, to evaluate the performance of HELQ and XAB2 as predictors." (PMID 35392433, 2022). "More importantly, we observed good accordance of HELQ and XAB2 expressions between ascites tumor cells and paired tumor tissues tumor tissues in our study." (PMID 35392433, 2022). "Consistent with ascites samples, a trend toward platinum resistance enrichment was observed in cases with high expression of HELQ and XAB2 in paired tumor tissues, which supported HELQ and XAB2 as predictors of platinum resistance." (PMID 35392433, 2022). "In this study, the high expression of HELQ and XAB2 in ascites tumor cells may lead to an increase of the ability of DNA damage repair, such as the HR or NER pathway, and a decrease in apoptosis, which led to tumor cell tolerance to platinum drugs." (PMID 35392433, 2022). "Hence, the assessment of HELQ and XAB2 expression levels in ascites tumor cells may help clinicians to design individualized treatment strategies for HGSC patients." (PMID 35392433, 2022). "To confirm the correlation between HELQ and XAB2 expressions and platinum-based chemotherapy response in HGSC, we noticed that high expression of HELQ and XAB2 in ascites tumor cells were strongly correlated with platinum resistance." (PMID 35392433, 2022). "Moreover, IHC revealed that the ratio of Ki67-positive cells and PCNA-positive cells was higher in the XAB2 overexpression group, while the ratio was lower in the XAB2 knockdown group, supporting the role of XAB2 in promoting CRC tumor growth." (PMID 40069750, 2025). "We observed platinum resistance enrichment in the high expression of HELQ (9/15 vs. 3/45, P < 0.001) and XAB2 (7/15 vs. 5/45, P = 0.006), suggesting that HELQ and XAB2 expressions in ascites tumor cells could be predictors of platinum resistance in HGSC." (PMID 35392433, 2022). "Our current finding showed that HELQ and XAB2 expressions in the ascites tumor cells correlated with HGSC patient's response to platinum-based chemotherapy and clinical outcomes indicate the potentiality of HELQ and XAB2 as independent biomarkers to predict HGSC patients' response to platinum drugs." (PMID 35392433, 2022). "Subsequent analyses of HELQ and XAB2 expressions in ascites tumor cells and clinical data showed statistically significant increased distribution of platinum resistance in patients with high-expression of HELQ (P < 0.001) and XAB2 (P = 0.006)." (PMID 35392433, 2022).
XAB2 also shares sentences with these, for which no sentence is quoted: Fanconi anemia (1 paper); multiple sclerosis (1); rectal adenocarcinoma (1); Serous Ovarian Cancer (1).